MAPKAP1 (MAPK associated protein 1)
Description:
Component of the mechanistic target of rapamycin complex 2 (mTORC2), which transduces signals from growth factors to pathways involved in proliferation, cytoskeletal organization, lipogenesis and anabolic output. In response to growth factors, mTORC2 phosphorylates and activates AGC protein kinase family members, including AKT (AKT1, AKT2 and AKT3), PKC (PRKCA, PRKCB and PRKCE) and SGK1. In contrast to mTORC1, mTORC2 is nutrient-insensitive. Within the mTORC2 complex, MAPKAP1/SIN1 acts as a substrate adapter which recognizes and binds AGC protein kinase family members for phosphorylation by MTOR. mTORC2 plays a critical role in AKT1 activation by mediating phosphorylation of different sites depending on the context, such as 'Thr-450', 'Ser-473', 'Ser-477' or 'Thr-479', facilitating the phosphorylation of the activation loop of AKT1 on 'Thr-308' by PDPK1/PDK1 which is a prerequisite for full activation. mTORC2 catalyzes the phosphorylation of SGK1 at 'Ser-422' and of PRKCA on 'Ser-657'. The mTORC2 complex also phosphorylates various proteins involved in insulin signaling, such as FBXW8 and IGF2BP1 (By similarity). mTORC2 acts upstream of Rho GTPases to regulate the actin cytoskeleton, probably by activating one or more Rho-type guanine nucleotide exchange factors. mTORC2 promotes the serum-induced formation of stress-fibers or F-actin. MAPKAP1 inhibits MAP3K2 by preventing its dimerization and autophosphorylation. Inhibits HRAS and KRAS independently of mTORC2 complex. Enhances osmotic stress-induced phosphorylation of ATF2 and ATF2-mediated transcription. Involved in ciliogenesis, regulates cilia length through its interaction with CCDC28B independently of mTORC2 complex. [Isoform 4]: In contrast to isoform 1, isoform 2 and isoform 6, isoform 4 is not a component of the a mTORC2 complex.
Synonyms: MIP1; SIN1; MGC2745; JC310; SIN1b; SIN1g
Tractability: Small molecule: a structure with a bound ligand is known; a high-quality ligand is known. Antibody: UniProt places it where antibodies can reach, with high confidence; its Gene Ontology location is reachable by antibodies, with high confidence. PROTAC: ubiquitination databases record sites on it; its protein half-life has been measured; a small molecule that binds it is known.
Gene: Protein-coding gene on chromosome 9 (125,437,393 to 125,707,266, reverse strand). Ensembl gene ENSG00000119487.
Subcellular location: Cell membrane; Endoplasmic reticulum membrane; Early endosome membrane; Late endosome membrane; Lysosome membrane; Golgi apparatus membrane; Mitochondrion outer membrane; Cytoplasm, perinuclear region; Nucleus; Cell membrane (Isoform 1); Cell membrane (Isoform 2); Cell membrane (Isoform 4); Cytoplasm, cytosol; Cytoplasm (Isoform 6)
Subcellular location (Human Protein Atlas): Nucleoplasm; Cytosol; Primary cilium
Pathways (Reactome):
Disease: Constitutive Signaling by AKT1 E17K in Cancer; Dengue virus modulates apoptosis
Signal Transduction: PIP3 activates AKT signaling; VEGFR2 mediated vascular permeability
Cellular responses to stimuli: High laminar flow shear stress activates signaling by PIEZO1 and PECAM1:CDH5:KDR in endothelial cells
Immune System: CD28 dependent PI3K/Akt signaling
Gene Ontology:
Molecular function: enzyme-substrate adaptor activity; molecular adaptor activity; phosphatidic acid binding; phosphatidylinositol-3,4,5-trisphosphate binding; phosphatidylinositol-3,4-bisphosphate binding; phosphatidylinositol-3,5-bisphosphate binding; phosphatidylinositol-4,5-bisphosphate binding; protein binding; protein kinase binding; protein serine/threonine kinase activity; small GTPase binding
Biological process: negative regulation of Ras protein signal transduction; substantia nigra development; TORC2 signaling; cellular response to insulin stimulus; cellular response to nutrient levels; cytoskeleton organization; negative regulation of apoptotic process; negative regulation of insulin receptor signaling pathway; positive regulation of cell growth; regulation of cellular response to oxidative stress
Cellular component: cytoplasm; early endosome; early endosome membrane; endoplasmic reticulum; endoplasmic reticulum membrane; Golgi apparatus; Golgi membrane; late endosome; late endosome membrane; lysosomal membrane; lysosome; mitochondrial outer membrane; nucleoplasm; nucleus; plasma membrane; TORC2 complex; cytosol; perinuclear region of cytoplasm
Genetic constraint (gnomAD): Loss-of-function variants: 13 observed, 56.02 expected, observed/expected ratio (o/e) 0.23, 90% interval 0.15 to 0.37. The upper end of that interval is the gene's LOEUF score, 0.37, which puts it in group 1 of 6, group 1 being the genes least tolerant of losing a copy. Missense variants: 387 observed, 634.18 expected, observed/expected ratio (o/e) 0.61, 90% interval 0.56 to 0.66. Synonymous variants: 206 observed, 243.74 expected, observed/expected ratio (o/e) 0.85, 90% interval 0.75 to 0.95.
Homologues: Orthologues: chimpanzee MAPKAP1 (100% identical), macaque MAPKAP1 (100% identical), pig MAPKAP1 (99% identical), guinea pig MAPKAP1 (99% identical), mouse Mapkap1 (97% identical), rat Mapkap1 (97% identical), rabbit MAPKAP1 (93% identical), tropical clawed frog mapkap1 (85% identical), zebrafish mapkap1 (82% identical), dog MAPKAP1 (73% identical), Drosophila melanogaster Sin1 (30% identical), Caenorhabditis elegans sinh-1 (25% identical).
Diseases named in the same sentence as MAPKAP1 in open-access papers:
MAPKAP1 is named in the same sentence as 53 diseases in open-access papers, as found by Europe PMC text mining. Sharing a sentence is not in itself a finding about the gene and the disease. The quoted sentences say what the papers report.
cervical cancer (3 papers, 2015 to 2022). A primary or metastatic malignant neoplasm involving the cervix. "Long non-coding RNA CASC9-1 promotes cervical cancer progression by targeting miR-383 to upregulate MAPKAP1." (PMID 36071480, 2022).
colorectal cancer (2 papers, 2023 to 2025). A primary or metastatic malignant neoplasm that affects the colon or rectum. "In colorectal cancer, PDCD4 inhibits SIN1 (MAPKAP1) translation, to reduce cell invasion." (PMID 39890941, 2025).
Hepatic fibrosis (2 papers, 2014 to 2025). The presence of excessive fibrous connective tissue in the liver. "Therefore, we infer that MAPKAP1 would play a central role by receiving and responding to input stress signals from various pathways and regulating transduction of signals in the hepatic fibrosis pathogenesis." (PMID 25153992, 2014).
melanoma (2 papers, 2012 to 2019). A malignant, usually aggressive tumor composed of atypical, neoplastic melanocytes. "The MAPKAP1 deletion associated gene signature was greatly enriched in N-Ras wild-type melanoma patient data as compared to N-Ras mutant tumors, consistent with the premise that a portion of N-Ras impacts are mediated through mTORC2 components." (PMID 31497244, 2019). "Subsequent experiments demonstrated that the mTORC2 components, Rictor and MAPKAP1, preferentially co-immunoprecipitated with oncogenic compared to wild-type Ras and were required for mutant Ras and mTOR proximity in mutant N-Ras melanoma cells." (PMID 31497244, 2019).
mood disorder (2 papers, 2019 to 2023). A cognitive disorder a disturbance in which the person's mood is hypothesized to be the main underlying feature. "Rs12341778 on MAPKAP1, with the mapped genes previously linked to mood disorder, also showed GWS associations with smoking cessation." (PMID 37147289, 2023).
oral cancers (1 paper, 2018). "MAPKAP1, TSC1 and RPTOR are also involved in mTOR signaling, which has been associated with tumor growth and immune regulation in the local microenvironment of oral cancers." (PMID 30308005, 2018).
schistosomiasis (1 paper, 2014). An infectious disease caused by parasitic trematodes of the genus Schistosoma that colonize human blood vessels and release eggs that can cause granulomatous reactions leading to acute (swimmer's itch or acute schistosomiasis syndrome) or chronic disease. "Knowledge of the role of MAPKAP1 in schistosomiasis triggers efforts to clarify the mechanisms of HF and hepatosplenic disease." (PMID 25153992, 2014).
Schistosomiasis japonica (1 paper, 2014). Schistosomiasis caused by Schistosoma japonicum. "Lastly, we investigated the statistical interactions between MAPKAP1 (rs10118570) and GRP78 (rs391957) with respect to schistosomiasis japonica in the discovery, replicative and combined cohorts." (PMID 25153992, 2014).
subarachnoid hemorrhage (1 paper, 2014). A serious neurological disorder characterized by intracranial hemorrhage into the subarachnoid space. "MAPKAP1 polymorphisms were significantly associated with the prevalence of subarachnoid hemorrhage." (PMID 25153992, 2014).
vitiligo (1 paper, 2021). Generalized well circumscribed patches of leukoderma that are generally distributed over symmetric body locations and is due to autoimmune destruction of melanocytes. "MAPKAP1 (TOR signaling pathway) promotes dark epithelial pigmentation, GRL101 (rhodopsin signaling pathway) is an ortholog of the pigment dispersing factor, and enolase (glycolysis/gluconeogenesis pathway) is a biomarker of vitiligo, a human pigmentation disorder affecting melanocytes." (PMID 33815466, 2021).
cancer (23 papers, 2014 to 2025). A tumor composed of atypical neoplastic, often pleomorphic cells that invade other tissues. "We subsequently investigated the correlations between the CNV of ISCA1 and the RNA expression of FRGs and reported that the ISCA1 CNV was positively correlated with TSC1, FXN, BRD3, and MAPKAP1 in most cancer types." (PMID 39766805, 2024). "We searched the PUBMED database (‘SIN1’ OR ‘MAPKAP1’) AND (‘neoplasm’ OR ‘cancer’) and found 179 results." (PMID 37877351, 2023). "Finally, we assayed the ability of the MAPKAP1 deletion to impede in vivo tumorigenesis of oncogenic Ras-dependent cancer cells." (PMID 31497244, 2019). "Additionally, mTORC2/AKT signaling activates proliferative cell cycles in cancer cells, leading to tumor development, through the binding of mutated rat sarcoma virus (RAS) proteins to mTOR components of mTORC2 and mitogen-activated protein kinase-associated protein 1 (MAPKAP1)." (PMID 39349424, 2024). "Expression of the MAPKAP1 deletion decreased cell cycle and DNA replication gene expression in mutant Ras-dependent cancer cell lines, mirroring the transcripts specifically decreased when we knocked down either RICTOR or MAPKAP1 in the same cancer cells." (PMID 31497244, 2019). "Critically, expression of the MAPKAP1 deletion hindered the subcutaneous growth of H-Ras mutant bladder cancer, K-Ras mutant colon cancer and N-Ras mutant melanoma cancer cells, but not tumorigenesis of cancer tissue type-matched wild-type Ras cells." (PMID 31497244, 2019).
infection (3 papers, 2014 to 2016). The state of being infected such as from the introduction of a foreign agent such as serum, vaccine, antigenic substance or organism. "We identified a SNP (rs10118570 GG in mitogen-activated protein kinase associated protein 1, MAPKAP1) contributes to anti-infection (adjusted OR = 0.35) and anti-fibrogenesis (adjusted RR = 0.44) in the discovery study." (PMID 25153992, 2014). "We identified a strong association of MAPKAP1 (rs10118570) with anti-infection and anti-fibrosis in chronic schistosomiasis japonica." (PMID 25153992, 2014). "We conclude that MAPKAP1 may represent a novel anti-infection and anti-fibrogenesis genomic locus in chronic schistosomiasis japonica." (PMID 25153992, 2014).
digestive tumours (1 paper, 2024). "Our analysis of PPI networks identified 11 hub genes (Myd88, Traf6, Irf7, Cdk4, Ccnd2, Mapkap1, Prr5, Mpp3, Serpinb6b and Pvrl3) that were implicated in digestive tumours." (PMID 38434966, 2024). "The PPI networks identified 10 hub genes that were implicated in digestive tumour immunotherapy target TIM-3 (Myd88, Traf6, Irf7, Cdk4, Ccnd2, Mapkap1, Prr5, Mpp3, Serpinb6b and Pvrl3)." (PMID 38434966, 2024).
MAPKAP1 also shares sentences with these, for which no sentence is quoted: tumor (20 papers); neuroblastoma (4); osteosarcoma (4); breast carcinoma (3); neurodegenerative disease (3); papillary thyroid cancer (3); thyroid cancer (3); colon carcinoma (2); hepatocellular carcinoma (2); ovarian carcinoma (2); pancreatic cancer (2); prostate carcinoma (2); Alzheimer disease (1); arterial hypertension (1); cervical squamous cell carcinoma (1); diverticular disease (1); endothelial dysfunction (1); Ewing sarcoma (1); gastric cancer (1); glioma (1); head and neck cancer (1); Hyperglycemia (1); lentivirus infection (1); leukemia (1); lipoma (1); liver cancer (1); lung carcinoma (1); medullary thyroid cancers (1); mental illness (1); microcephaly (1).
A further 10 diseases each share a sentence with MAPKAP1 in 1 paper.